VN1R17P (vomeronasal 1 receptor 17 pseudogene)
Description:
Putative pheromone receptor.
Gene: Processed pseudogene on chromosome 1 (247,236,868 to 247,237,957, reverse strand). Ensembl gene ENSG00000235818.
Subcellular location: Cell membrane